INS (insulin)
Diseases named in the same sentence as INS in open-access papers (continued):
Sharing a sentence is not in itself a finding about the gene and the disease.
Insulin resistance (continued). "However, we wanted to find out how, under conditions of induced insulin resistance, reducing DAG content would affect the insulin pathway and whether it would improve muscle glucose uptake." (PMID 33036203, 2020). "Insulin resistance refers to the condition in which the body’s response to insulin is insufficient; the body does not detect an increase in insulin secretion, and the insulin activity may also be ineffective." (PMID 32397662, 2020). "This may contribute modestly to the observed insulin resistance, but it is not conceivable that the minute reduction in insulin levels acts significantly to the decrease in insulin sensitivity." (PMID 33151986, 2020). "In particular, it is well known that obesity is characterized by insulin resistance and low-grade systemic inflammation, which may affect the oncological outcomes of NMIBC patients as a result of insulin, insulin-like growth factor 1(IGF-1), cytokines, and growth factor effects." (PMID 33343662, 2020). "This is an interesting finding because if we consider intake of such a beverage in a non-exercise regime then the induction of insulin secretion may plausibly over time contribute to insulin resistance." (PMID 32977648, 2020). "In addition, the HFD-fed Sirt1 heterozygous mice (Sirt1+/–) present with more severe insulin resistance, compared with wild-type mice, which may be mediated by reductions in adipose GLUT4 translocation and insulin-stimulated glucose transport." (PMID 33193730, 2020). "Recent studies have advocated the use of TyG index as a reliable and simple biomarker of insulin resistance in clinical practice since this index does not require quantification of insulin and may be reliably used in patients treated with insulin." (PMID 32967240, 2020). "Also, the diabetic and non-diabetic CHC population exhibited normal serum insulin and insulin resistance." (PMID 33520544, 2020). "Indeed, the LCSFA palmitate is sufficient to induce hypothalamic insulin resistance, whereas long-chain mono-unsaturated fatty acids do not alter insulin sensitivity." (PMID 32456175, 2020). "Subsequent studies employing insulin stimulation prior to euthanasia also revealed that 17α-E2 robustly increased liver AKT and FOXO1 phosphorylation in male WT mice, indicating a reversal of obesity-related hepatic insulin resistance and increased control of gluconeogenesis." (PMID 33289482, 2020). "Although JNK is known to cause serine phosphorylation of IRS1, which is linked to insulin resistance, loss of the described JNK-induced Ser307 IRS1 phosphorylation actually deteriorates insulin action and metabolism, questioning direct negative effects of JNK activation on insulin action." (PMID 32456175, 2020). "Moreover, we were not able to incorporate additional markers for evaluating insulin resistance and insulin secretion, such as the Matsuda index and the insulin secretion-sensitivity index-2." (PMID 33207657, 2020). "In heterozygous pancreatic beta-cell-specific glucokinase knockout mice (βGck +/− mice), which exhibit impaired insulin secretion in response to glucose without insulin resistance, the mRNA expression levels of Egfr were also much higher in liver than in adipose tissue and skeletal muscle." (PMID 33005239, 2020). "The presence of selective insulin resistance in one organ or tissue and not another is well recognised, particularly in the context of obesity, where insulin resistance in muscles may be counterbalanced by insulin sensitivity in adipose tissue stores." (PMID 32707917, 2020). "Furthermore, GS-0976 did not increase plasma glucose, insulin levels or induce insulin resistance in NASH patients." (PMID 31990961, 2020). "Although the precise cellular type that develops insulin resistance in the brain has not yet been identified, recent studies suggest that cortical neurons develop resistance to insulin after prolonged exposure to high insulin concentrations." (PMID 31936865, 2020).
Insulin resistance (continued). "Similarly, most of the randomized trials and meta-analysis evaluating the effect of metformin add-on in adolescents with T1D found that metformin reduced the total insulin dose and BMI, suggesting improvements in insulin resistance, but did not improve HbA1c." (PMID 33457425, 2020). "In contrast, in KK-Ay mice fed high-fat diet (a model for T2D possessing insulin resistance), dietary supplementation with EA (0.1%) for 68 days did not affect serum glucose or insulin, although it reduced serum resistin and improved serum lipid profile and hepatic steatosis." (PMID 33287432, 2020). "Moreover, levels of insulin were significantly higher in F1m dams (F1c: 0.2 ± 0.04 ng/mL vs. F1m: 0.4 ± 0.1 ng/mL, p = 0.012), accompanied by elevated HOMA-IR (F1c: 0.6 ± 0.1 vs. F1m: 1.3 ± 0.2, p = 0.013), indicating a state of insulin resistance." (PMID 32545776, 2020). "Furthermore, the clinical finding that apoE4 carriers, unlike non-carriers, do not cognitively benefit from intranasal insulin administration is suggestive of the fact that they have increased insulin resistance." (PMID 32075060, 2020). "This may be because the previous analysis was looking at insulin resistance and not the correlation between c-peptide and insulin." (PMID 32375229, 2020). "Insulin signal transduction involves the insulin receptor substrate (IRS), phosphatidylinositol-3-kinase (PI3K) and serine/threonine kinase (Akt), and the glucose transporter (GLUT), which are the foci of current research on the molecular mechanism of insulin resistance." (PMID 32566690, 2020). "In contrast, the overexpression of Sirt1 in skeletal muscle in vivo does not improve insulin resistance and had little impact on mitochondrial metabolism, suggesting that the overexpression of Sirt1 protein is not the single factor involved in insulin sensitization of skeletal muscle." (PMID 32796716, 2020). "The serum OC level did not correlate with insulin levels and insulin resistance index." (PMID 33911828, 2020). "BED patients with obesity actually have a significantly worse metabolic profile in comparison with non-BED patients, including higher fasting insulin levels, insulin resistance estimated through HOMA index, HbA1c (glycated hemoglobin), uric acid blood levels and visceral fat accumulation." (PMID 32717793, 2020). "Although insulin resistance is a characteristic of individuals with MetS, MetS may appear without the presence of elevated insulin concentrations." (PMID 33374992, 2020). "It is the progression into β-cell failure that causes the transition into T2D, as the β-cells are no longer able to compensate for insulin resistance by increasing insulin secretion, and β-cell JNK1/2 are one of the key players in causing such a defect in compensation." (PMID 32183037, 2020). "Change in insulin resistance may be minimal in the absence of weight change; or obscured by the lack of standardization of insulin assays that hinder the comparison of assays over time." (PMID 31992297, 2020). "Studies, including ours, have suggested that prolonged exposure to hyperinsulinemia might induce common molecular defects in the insulin/IGF-1 signaling pathway leading to both peripheral and β-cell insulin resistance and therefore contribute to the development of T2DM." (PMID 32150819, 2020). "Insulin suppressed hepatic glucose production but could not reverse tunicamycin effect suggesting insulin resistance induced by tunicamycin through stimulation of ER stress in the hepatocytes." (PMID 32180905, 2020). "Second, long term negative actions might occur during states of insulin resistance and increased insulin secretion, or hyperinsulinemia, which are non-physiological." (PMID 32150819, 2020). "Vice versa, high insulin-mediated β-cell insulin resistance may interfere with the ability of the β-cell to promote normal endothelial function and modulate islet capillary density and blood flow." (PMID 32150819, 2020).
Insulin resistance (continued). "The lack of a control group with similar age but normal weight or insulin sensitivity prevents us from drawing conclusions as to whether aging, overweight, or insulin resistance it responsible for the lack of rhythmicity." (PMID 32659272, 2020). "Similarly, in adipose and liver tissue, disruption of the insulin signaling IRS‐PI3K‐Akt axis leads to severe glucose intolerance and insulin resistance, as described by many INSR, IRS, and Akt knockout studies investigating their effects on proximal insulin signaling and body glucose homeostasis." (PMID 33038072, 2020). "The prevalence of insulin resistance (HOMA-IR) after HCV clearance was significantly lower, compared to baseline (5.3 ± 6.1 to 2.5 ± 1.9, p < 0.001), which is primarily attributable to a significant decrease of fasting insulin levels (18.9 ± 17.3 to 11.7 ± 8.7; p = 0.002)." (PMID 32825571, 2020). "Although there is a link in the dysregulation of glucose, insulin, and lipids in insulin resistance, the role of lipids may be affected by or influenced by pathways independent of insulin resistance." (PMID 32393179, 2020). "Considering patients with insulin resistance at baseline (HOMA-IR > 2.5 and Matsuda Index < 2.5; n = 5), reduced mean fasting insulin levels (16.3 ± 4.9 versus 13.5 ± 3.5 mcU/mL; p=0.029) and increased insulin sensitivity index QUICKI (0.317 ± 0.013 versus 0.327 ± 0.009; p=0.025) were found." (PMID 33204260, 2020). "Hence, chronic exposure of cells to high ambient insulin concentrations causes an imbalance of cellular responses because of the downregulation of some insulin signaling pathways (“insulin resistance”) but not of others." (PMID 32819363, 2020). "In addition, HFD rats had higher blood glucose and total cholesterol levels at the 4th, 6th and 8th week and higher plasma insulin concentration and HOMA-IR level, the index of insulin resistance at the 8th week, supporting that HFD successfully induced features of metabolic syndrome." (PMID 32354071, 2020). "Interestingly, although insulin resistance is involved in the pathogenesis of low concentrations of high-density lipoprotein (HDL) cholesterol, HDL itself may stimulate insulin secretion and prolong β-cell survival." (PMID 32245262, 2020). "The authors reported a positive correlation between insulin resistance and weight gain; however, there was no control group in this study, while other reports have demonstrated a rapid improvement in insulin sensitivity after two days of CPAP therapy that remained stable for three months." (PMID 32872644, 2020). "Moreover, subjects with T2DM were reported to have significantly higher plasma levels of FGF21 than insulin-sensitive controls, with FGF21 levels positively correlated with BMI, HOMA-IR, and Matsuda index, suggesting a strong correlation with insulin resistance." (PMID 32158768, 2020). "Similarly, insulin resistance accelerates progression to T1D in islet autoantibody-positive relatives in whom insulin secretion is reduced but does not affect progression when insulin secretion is relatively well preserved." (PMID 31520124, 2020). "However, in the present study, insulin resistance and insulin sensitivity indices were not improved by sage tea treatment." (PMID 32523881, 2020). "Moreover, obesity is associated with various metabolic disorders that can lead to an increase in cortisol, leptin and insulin levels, with consequent dysregulation of the HPA axis and insulin resistance which can further induce inflammation and worsen depression." (PMID 32545890, 2020). "Thus, although Pdgfrα-Cre mediated knockout of Ahr appeared to offer some protection against HFD-induced insulin resistance at certain time points, the overall effect on insulin sensitivity was not considered significant." (PMID 32730300, 2020).
Insulin resistance (continued). "Similarly, the ITT blood test results and the corresponding AUC values also showed a significant increase in insulin resistance in the HFD group, indicating intragastric administration of PC improved the glucose metabolism and insulin response in obese female mice." (PMID 33282873, 2020). "However, daily doses of DPP4 inhibitors do not lower plasma insulin in patients with insulin resistance." (PMID 32211075, 2020). "With insulin resistance, the cells do not respond normally to insulin." (PMID 33425218, 2020). "We did not see any changes in fasting glucose, insulin or insulin resistance (HOMA)." (PMID 32340150, 2020). "However, there was no amelioration in insulin sensitivity (IS) and insulin resistance (IR) in young women." (PMID 32148647, 2020). "Additionally, patients with primary insulinoma and no prior medical history of metabolic syndrome acquired insulin resistance, and complete resection of the insulinoma restored normal glucose metabolism and insulin sensitivity." (PMID 32230718, 2020). "Overall, these observations suggest that mechanisms directing the negative action of ceramide on muscle insulin sensitivity are rather complex, and may imply to consider SL subcellular localization in order to fight insulin resistance." (PMID 32849282, 2020). "It should be noted that in these studies, no lipid infusion was used and therefore, no lipid-induced insulin resistance occurred and the uptake of carnitine may have been more efficiently stimulated by insulin." (PMID 32976523, 2020). "The addition of insulin to high glucose medium, reflecting a condition of high fasting glycaemia and insulin resistance, led to a significant increase in miR-340 levels, compared to cells cultured without insulin, indicating a critical effect of insulin on miR-340 expression." (PMID 32512799, 2020). "NF-κB activation is particularly involved on the mechanisms of insulin resistance through the induction of several inflammatory proteins, such as iNOS and NAPDH oxidase, inducing nitrogen and oxygen radical species formation and the consequent blockage of insulin cascade." (PMID 32690985, 2020). "When HOMA-IR was calculated using fasting blood glucose and insulin levels measured at 12 weeks, the SA-treated groups (SA100 group: 4.7±0.4) showed a significantly lower value than the vehicle group (21.5±3.1), suggesting that insulin resistance was improved by SA treatment." (PMID 32218700, 2020). "Besides, it is reported that the receptor of AGTR1 is activated on liver cells in initiation of insulin resistance, which further enlarges the activation of hepatocellular NF-κB signaling and NF-κB signaling is responsible for negative crosstalk with insulin." (PMID 32382544, 2020). "Obesity promotes insulin resistance in target tissues and has detrimental effects on β cells, resulting in reduction of insulin content, abnormally elevated insulin release in the absence of stimuli, diminished capacity to secrete insulin in response to glucose, and increased β cell apoptosis." (PMID 32286278, 2020). "Furthermore, EMP significantly reduced (p < 0.05) the HOMA-IR index and decreased the serum insulin level, indicating that EMP could suppress hyperinsulinemia and improved insulin resistance." (PMID 32256445, 2020). "Furthermore, the mechanisms of insulin resistance in PCOS and metformin’s actions in improving the action of insulin are still largely unknown." (PMID 32385376, 2020). "Although ADPN deficiency is associated with peripheral insulin resistance in mice and humans, causing diabetes, whether ADPN is associated with cerebral insulin sensitivity has not been documented." (PMID 32188008, 2020). "Furthermore, when all the participants were categorized into two groups with and without insulin resistance, the prevalence of thyroid nodules was significantly higher in insulin resistant group compared to non-insulin resistant group." (PMID 32874434, 2020).
Insulin resistance (continued). "Moreover, in a 2007 study on exercise and insulin resistance in obese children, it was determined that exercise alone, independent of body composition changes, reduced insulin resistance." (PMID 33376604, 2020). "Further consideration revealed a variety of markers unambiguously attributed to DF and these markers can be combined in line with both negative regulation of insulin signaling and shift the glucose uptake to non-oxidative utilization as hallmarks of insulin resistance." (PMID 32326243, 2020). "Hence, high fasting plasma NEFA concentrations are associated with glucose intolerance, regardless of the existence of previous insulin resistance or defects in insulin secretion." (PMID 32290082, 2020). "However, it induces insulin resistance by the disruption of insulin signaling and induces non-alcoholic fatty liver disease (NAFLD) via the mechanism of hepatic lipid accumulation due to the activity of the ERK/JNK pathway." (PMID 33123164, 2020). "In clinical practice, insulin dosage in diabetics, if reduced, may not indicate low insulin resistance but rather a failure in pancreatic beta-cells function." (PMID 31914140, 2020). "Although it is not known why hepatic de novo lipogenesis, an insulin-sensitive pathway, is activated in insulin resistance, the prevalence of NAFLD is up to three times higher in patients with type 2 diabetes compared to the general population (~90% versus 30%)." (PMID 32182914, 2020). "However, subjects with T2DM nearly always have insulin resistance and an absent or impaired first‐phase insulin response to glucose testing." (PMID 33030304, 2020). "However, the mitogenic Ras/Raf/MAPK (JNK) pathway is unaffected during insulin resistance or is even upregulated by the compensatory hyperinsulinemia, because Shc Tyr phosphorylation by insulin is not affected." (PMID 32183037, 2020). "As glucose uptake is regulated by insulin-induced phosphorylated Akt, we hypothesized that insulin resistant 3T3-L1 and SGBS would show decreased internalization of glucose, as previously observed in similar models of insulin-induced insulin resistance in 3T3-L1." (PMID 32718202, 2020). "Reduced insulin clearance may be driven by impaired hepatic or peripheral clearance, but it is not yet clear how obesity versus insulin resistance influences hepatic or peripheral insulin clearance." (PMID 32860984, 2020). "Women with heavier insulin resistance in the postpartum period are more likely develop prediabetes, while decreased β-cell function contributes more to T2DM development.β were used to assess insulin resistance and insulin secretion levels with different glucose statuses." (PMID 32184821, 2020). "One thing that needs to be mentioned is that no matter whether the insulin secretion is inadequate or insulin resistance is too severe, both were compared to normal pregnancy." (PMID 32184821, 2020). "In addition, insulin resistance expressed as HOMA-IR decreased significantly during the HCM diet, indicating that a carbohydrate distribution of 50% in the morning favors lower blood glucose and improvement in insulin sensitivity in women with GDM." (PMID 32069857, 2020). "Insulin resistance describes the phenomenon when a normal or increased insulin level could not induce a proper metabolic response, such as insulin-induced glucose uptake." (PMID 33142995, 2020). "When we checked for insulin signaling in the aged liver by immunoblotting, we noticed the levels of total INSRB protein was reduced (p=0.0220), which might be due to chronic exposure to hyperinsulinemia that can, in part, lead to insulin resistance." (PMID 33345777, 2020). "The clinical efficacy of reduction in serum insulin levels in PCOS suggests that the reproductive abnormalities may be directly related to hyperinsulinemia rather than insulin resistance." (PMID 32385376, 2020).